CCNE1 (cyclin E1)
Diseases named in the same sentence as CCNE1 in open-access papers (continued):
Sharing a sentence is not in itself a finding about the gene and the disease.
serous carcinoma (16 papers, 2010 to 2025). "High cytoplasmic cyclin E1 expression showed a significant association with serous carcinoma (adjusted p value < 0.0001)." (PMID 38612869, 2024). "Multi‐institutional validation of the prognostic value of cyclin E1 high‐level amplification and overexpression in 3029 tubo‐ovarian high‐grade serous carcinoma cases support its value as a prognostic biomarker in this disease." (PMID 36572991, 2023). "We sought to characterize the variability of CCNE1 amplification among metastatic sites of CCNE1 amplified high grade serous carcinoma (HGSC) cases to investigate the feasibility of targeting this alteration for therapeutic purposes." (PMID 34485660, 2021). "•CCNE1 amplification is conserved among metastatic sites in CCNE1-amplified high-grade serous carcinomas." (PMID 34485660, 2021). "•Digital droplet PCR can be used to quantify CCNE1 copy number from archival specimens of high-grade serous carcinomas." (PMID 34485660, 2021). "Using SNP arrays, Kuhn and colleagues recently reported CCNE1 amplification in 26.1% uterine serous carcinomas." (PMID 27582547, 2017). "Furthermore, combining poly (ADP-ribose) polymerase (PARP) and WEE1 inhibitors has shown promising activity in p53abn/CCNE1-amplified serous carcinomas, targeting the specific DNA damage response vulnerabilities created by these alterations." (PMID 40940815, 2025). "CCNE1 gain and RB1 loss could potentially impair actionability in some patients with high-grade serous carcinomas." (PMID 33947352, 2021). "It was reported that CCNE1, which was amplified in approximately 20% of high-grade serous carcinomas (HGSC) of the ovary, might be a potential biomarker of CDK inhibitors and proteasome inhibitors." (PMID 29433585, 2018). "Interestingly, increased expression of CCNE1 has recently been shown in serous tubal intraepithelial carcinoma (STIC), a proposed precursor for high-grade serous carcinoma." (PMID 21103391, 2010). "No CCNE1 amplification was detected in low-grade serous carcinoma." (PMID 41331376, 2025). "CCNE1 overexpression is observed in ovarian high-grade but not low-grade serous carcinomas." (PMID 32295618, 2020).
sarcoma (15 papers, 2012 to 2025). A usually aggressive malignant neoplasm of the soft tissue or bone. "After a brief in vitro expansion at 1% oxygen, MSCs were transformed into sarcoma cells via overexpression of Ccne1 or Vgll3, using viral vectors which also encode a red fluorescent protein (dsRED) reporter for tracing." (PMID 38509063, 2024). "Through an integrative transcriptional and functional approach, we investigated how CIC-DUX4 sarcomas survive in a CCNE1-mediated high-replication-stress state through increased dependence on the WEE1 kinase." (PMID 35315355, 2022). "To this end, we recently observed that CIC-DUX4 sarcoma is molecularly dependent on the CCNE/CDK2 complex: CIC-DUX4 acquires neomorphic function as a transcriptional activator to upregulate CCNE1, driving sarcoma growth and survival." (PMID 35315355, 2022). "Overexpression of CCNE1 with high-level genomic amplification was identified in lung, stomach, sarcoma, and esophagogastric junction tumors." (PMID 28377632, 2017). "Thus, a key question remains how CIC::DUX4 sarcoma cells mechanistically repair DNA under CCNE1-mediated high replicative stress states prior to mitotic entry?" (PMID 40760094, 2025). "Thus, we demonstrate that CIC-DUX4 sarcomas transcriptionally upregulate CCNE1, compromising the G1/S checkpoint and conferring dependence on WEE1 to limit DNA damage–associated cell death." (PMID 35315355, 2022). "Accordingly, the immune-infiltrated Vgll3+ model showed a more robust response to the standard regimen of doxorubicin compared to the immune-excluded Ccne1+ model, suggesting that an inflamed sarcoma microenvironment may be favorable for chemotherapy responses." (PMID 38509063, 2024). "Therefore, we first used a reporter to distinguish sarcoma cells from the TME cells and profiled 12 independent Ccne1+ tumors by scRNA-seq to identify specific CAF markers." (PMID 38509063, 2024). "Since CIC-DUX4 transcriptionally upregulates CCNE1, which can induce a high-replicative-stress state in cancer, we hypothesized that WEE1 activity in CIC-DUX4 sarcomas may be an adaptive survival mechanism." (PMID 35315355, 2022). "In addition, as part of a mechanism of adaptation to CCNE1 upregulation, and the subsequent DNA damage and unscheduled mitotic entry, CIC–DUX4 sarcoma cells become particularly dependent on the G2/M cell cycle checkpoint WEE1." (PMID 36358827, 2022). "By analyzing data from TCGA sarcoma cohort, we further confirmeda strong positive correlation between RRM2 and cyclin B1, cyclin E1,and CHEK1 expression, as well as a negative correlation with TP53expression." (PMID 40834268, 2025). "Since CCNE1 expression is a clinically validated biomarker of WEE1 inhibitor response, we anticipate that individuals with CIC-DUX4 sarcomas, but not other small round blue cell tumors including ES or alveolar rhabdomyosarcoma, will benefit from WEE1 inhibitor treatment." (PMID 35315355, 2022).
gastric adenocarcinoma (10 papers, 2014 to 2024). "We identified CCNE1 amplification in 6.2% of esophageal adenocarcinoma samples, 7.0% of esophagogastric junction carcinoma, 4.2% of gastric adenocarcinoma samples, and 0.8% of esophageal squamous cell carcinoma." (PMID 38717153, 2024). "Among 341 esophagogastric tumors that underwent MSK-IMPACT sequencing, 9.2% (32 samples) harbored CCNE1 amplification, including 13/147 (8.8%) gastric adenocarcinoma samples, 12/137 (8.8%) EAC samples, and 7/57 (12.3%) EJC samples." (PMID 38717153, 2024). "In contrast, patients with CCNE1-amplified gastric adenocarcinoma exhibited a trend toward improved survival after receiving immunotherapy with a PD1 or PD-L1 inhibitor (HR = 0.541, 95% CI: 0.239–1.226, P = 0.134)." (PMID 38717153, 2024). "Similarly, we observed a higher frequency of CCNE1 amplification in gastric adenocarcinoma metastatic sites (6.0%) such as liver and lymph node metastases (11.1% and 10.4%, respectively) compared with primary tumors (3.9%; P = 0.037, Fisher exact test)." (PMID 38717153, 2024). "However, there were changes in other immune cell populations including decreased B cells and neutrophils in CCNE1-amplified tumors, as well as increased M1 macrophages in CCNE1-amplified gastric adenocarcinoma." (PMID 38717153, 2024). "One of the most strongly overrepresented pathways in both CCNE1-amplified gastric adenocarcinoma and EA was liver X receptor/retinoid X receptor activation, which has been linked to regulation of tumor growth, metastasis, and restriction of innate immune suppression in tumors." (PMID 38717153, 2024). "We identified CCNE1 amplification in approximately 7% of EA and 4% of gastric adenocarcinoma." (PMID 38717153, 2024). "Similarly, we found that CCNE1-amplified gastric adenocarcinoma harbored decreased B cells in addition to natural killer cells, whereas M1 macrophages showed increased representation." (PMID 38717153, 2024). "Finally, we analyzed specific immune-related gene signatures and found decreased IFN signatures in CCNE1-amplified EA, as well as trends toward decreased T cell–inflamed signatures in CCNE1-amplified EA and gastric adenocarcinoma." (PMID 38717153, 2024). "Notably, the inhibition of CDCA2 and CDCA5 activities in lung and gastric adenocarcinoma, respectively, resulted in the downregulation of CCNE1 expression, thereby inhibiting cancer cell proliferation and blocking it in the G1 phase." (PMID 36004205, 2022). "We observed a significant reduction in CDH1 mutations in CCNE1-amplified gastric adenocarcinoma versus nonamplified gastric adenocarcinoma (2.9% vs. 16.4%, P = 0.0002) as well as a reduction in CLDN18:ARHGAP fusions (0% vs. 6.8%); however, the frequency of RHOA mutations were similar." (PMID 38717153, 2024). "In addition, overexpression of NR5A2 was shown to promote the proliferation of gastric adenocarcinoma SGC-7901 cells via induction of cyclin E1, which may lead to the tumorigenesis of gastric cancer." (PMID 25514243, 2014). "We identified CCNE1 amplification in 6.2% of EA, 7.0% of EJC, and 4.2% of gastric adenocarcinoma samples; by contrast, CCNE1 was rarely amplified in ESCC (0.8%)." (PMID 38717153, 2024). "The median CCNE1 CN was 2.05, 2.05, 1.97, and 1.98 for EA, EJC, gastric adenocarcinoma, and ESCC, respectively." (PMID 38717153, 2024). "Researches have elucidated a mechanism within gastric adenocarcinoma where cyclin E1 (CCNE1) reorganization, prompted by altered TAD boundaries and interactions, correlates with heightened CCNE1 expression in primary tumors." (PMID 38374872, 2024). "In stomach/gastric adenocarcinoma, IGF2 and CCNE1 were identified as enhancer hijacking target genes in a cohort of 208 samples." (PMID 39051548, 2024).
gastric adenocarcinoma (continued). "In particular, among the 293 cases of gastric adenocarcinoma in TCGA database, MYC and CCNE1 amplification was detected in 11.9% and 10.6% patients, respectively, whereas in the CSF samples of our cohort, the MYC and CCNE1 amplification ratios were 46.7% and 53.3%, respectively." (PMID 37131253, 2023). "Moreover, microRNA-25 has an antiapoptotic role in human gastric adenocarcinoma cells, possibly via inhibition of FBXW7, thus promoting the expression of oncogenes such as CCNE1 and MYC35." (PMID 28566720, 2017). "We also observed increases in FBXW7 mutations in CCNE1-amplified EG adenocarcinoma, with a significant increase in CCNE1-amplified EA (8.9% vs. 2.4%, P = 0.002) and modest albeit not statistically significant increase in CCNE1-amplified gastric adenocarcinoma (5% vs. 3.4%, P = 0.39)." (PMID 38717153, 2024). "We also observed frequent PIK3CA mutations, associated with the EBV+ subtype, in gastric adenocarcinoma and EA, with a decrease in CCNE1-amplified versus nonamplified gastric adenocarcinoma (1.9% vs. 9.2%, P = 0.01) and a similar frequency in CCNE1-amplified versus nonamplified EA." (PMID 38717153, 2024).
liver fibrosis (10 papers, 2018 to 2025). "Our study revealed that deletion of Ccne1 only in HSCs substantially reduced liver fibrosis in both experimental settings, which was associated with reduced HSC activation." (PMID 37620309, 2023). "Accordingly, poor survival and reduced proliferation capacity of HSCs due to Ccne1 or Cdk2-deficiency is one possible mechanism to explain the substantial reduction of liver fibrosis in our study." (PMID 37620309, 2023). "Transition of hepatic stellate cells (HSCs) from a quiescent to an activated state is a sign of the onset of liver fibrosis, and this process is controlled by E-type cyclins (CcnE1, CcnE2) and their associated cyclin-dependent kinase 2 (Cdk2)." (PMID 30923657, 2019). "Thus, HSC-specific targeting of Ccne1 or Cdk2 in patients with liver fibrosis and high risk for HCC development could be therapeutically beneficial." (PMID 37620309, 2023). "Systemic administration of EVs loaded with Cas9 RNPs enable gene therapy for liver fibrosis via significant downregulation of cyclin E1 (CcnE1)." (PMID 39396032, 2024). "We provide evidence that the inactivation of Ccne1 only in HSCs is sufficient to substantially reduce liver fibrosis but also HCC development in CCl4-mediated murine injury models, which is at least partially dependent on its canonical kinase subunit CDK2." (PMID 37620309, 2023). "In summary, we provide evidence that Ccne1 expression in a small population of HSCs is sufficient to trigger extensive liver fibrosis and hepatocarcinogenesis in a Cdk2-dependent manner." (PMID 37620309, 2023). "To this end, we generated HSC-specific Ccne1 knockout mice and challenged these animals with a pure liver fibrosis model (CCl4) as well as with a model reflecting both liver fibrogenesis and hepatocarcinogenesis (DEN/CCl4)." (PMID 37620309, 2023). "Accordingly, constitutive, genetic knockout of Ccne1, but also systemic knockdown of Ccne1 using small interfering RNA (siRNA) prevented the onset of liver fibrosis in mice in the established carbon tetrachloride (CCl4) model." (PMID 37620309, 2023). "In previous work, we have demonstrated that the cell cycle mediator Ccne1 is essential for both initiation of liver fibrosis and HCC." (PMID 37620309, 2023). "In this context, we previously demonstrated that Ccne1 gene expression is induced in human and murine liver fibrosis." (PMID 37620309, 2023). "In this context, we recently showed that therapeutic targeting of Ccne1 in vivo using RNA interference is technically possible and capable of halting the progression of liver fibrosis." (PMID 34830835, 2021). "Recently, we demonstrated that Ccne1 is a suitable therapeutic target for the treatment of liver fibrosis." (PMID 34830835, 2021). "In the area of liver fibrosis research, Bangen and colleagues demonstrated that inhibiting the cell cycle protein cyclin E1 during liver fibrosis progression in CCl4-induced fibrosis significantly reduced disease severity." (PMID 31635053, 2019). "Here, we tested the hypothesis that HSCs are important effector cells for Ccne1-driven liver fibrosis and hepatocarcinogenesis." (PMID 37620309, 2023). "Thus, our study demonstrates that Ccne1 is an important modulator of HSCs in the course of liver fibrosis and cancer development." (PMID 37620309, 2023). "In addition, we already demonstrated that delivery of small inhibitory RNAs (siRNA) directed against CcnE1 can prevent both the onset of liver fibrosis and the progression of already existing fibrosis in mice." (PMID 32380742, 2020). "Increased expression of ccnE1 has been reported in human and mouse liver fibrosis." (PMID 30723492, 2018). "Thus, CcnE1 seems to be a suitable target for the treatment of liver fibrosis." (PMID 32380742, 2020). "Cyclin E1 is a protein kinase that regulates the proliferation of HSCs and its genome editing mediated by exosomeRNP resulted in a significant reduction of HSC activation, with consequent attenuation of liver fibrosis." (PMID 40852596, 2025).
liver fibrosis (continued). "Accordingly, knockout mice constitutively lacking CcnE1 were protected from carbon tetrachloride (CCl4)-induced liver fibrosis in vivo." (PMID 32380742, 2020). "Thus, our previous data does not exclude any of the main hepatic cell types from being a Ccne1-dependent driver of liver fibrosis or HCC." (PMID 37620309, 2023).
ovarian clear cell cancer (8 papers, 2018 to 2025). An invasive malignant neoplasm that arises from the ovary and is characterized by a predominance of clear and hobnail malignant epithelial cells. "Cyclin-E1 (CCNE1) is found as a potential therapeutic target for ARID1A-mutated ovarian clear cell carcinoma through synthetic lethality." (PMID 34680987, 2021). "In ovarian clear cell carcinoma, CCNE1 overexpression has been also associated with unfavourable prognosis." (PMID 32391646, 2020). "Multiple studies have provided evidence of an increase in the copy number of the CCNE1 gene and an up-regulation of CCNE1 in ovarian clear cell carcinoma." (PMID 38384812, 2024). "It was reported that 14.8% of patients with ovarian clear cell carcinomas developed CCNE1 copy number gain, which in turns is correlated with poor overall survival and outcome." (PMID 32628820, 2020).
glioblastoma (7 papers, 2016 to 2023). The most malignant astrocytic tumor (WHO grade IV). "In addition, cyclin E1 induction has been identified as a cause of temozolomide resistance in glioblastoma cells." (PMID 36142752, 2022). "We also determined that cyclin E1 associates with Lin proteins and with other components of the DREAM complex in mouse embryonic fibroblasts (MEFs) and in human glioblastoma T98G cells." (PMID 27828963, 2016). "We here show that SFRP2-overexpression decreases CCNE1, CCND1 and CCNB1, and at the same time decreases SOX2 protein and overall cell proliferation in glioblastoma cells." (PMID 34021259, 2021). "Top hub nodes from glioblastoma multiforme networks contain six matches, namely cyclin dependent kinase 2 (CDK2), cyclin A2 (CCNA2), cyclin B1 (CCNB1), erb-b2 receptor tyrosine kinase 2 (HER2), cyclin E1 (CCNE1), and cyclin D3 (CCND3)." (PMID 31952211, 2020).
leukemia (7 papers, 2012 to 2024). A malignant (clonal) hematologic disorder, involving hematopoietic stem cells and characterized by the presence of primitive or atypical myeloid or lymphoid cells in the bone marrow and the blood. "DBF activates the expression of genes encoding the proteins involved in leukemia cell survival, such as KIT, CTNNB1, CCNE1, NFKB1, E2F1, and downregulates the expression of CCND2, CCNA1, and FLT3 genes." (PMID 34564151, 2021). "Aberrant cyclin E expression or function, which results from CCNE1 amplification, overexpression, or impaired protein degradation, is frequently observed in various cancer types such as ovarian, breast, lung tumors, and leukemias." (PMID 39456601, 2024). "We utilized the data of gene expression profiling in samples with higher E2F1 expression and identified the genes associated with cell cycle progression (CCNA2, CCNE2, CCNB1, CCNB2 and, importantly, CCNE1) which were also found to be upregulated in leukemia cells exposed to DBF." (PMID 34564151, 2021). "The plasma cell leukemia cell line ARH77 displayed high level of CCNE1." (PMID 22558078, 2012). "have reported that both Bcl-2 and CCNE1 were positively regulated by NUDT21 and they mediated the promoting role of NUDT21 in human leukemia cells." (PMID 34660260, 2021).
uterine serous carcinoma (7 papers, 2017 to 2025). "In the survival analysis of all uterine serous carcinoma patients, those with CCNE1 amplification had significantly shorter median overall survival (97.3 months vs 44.3; HR (95%CI): 7.1 (10.03, 59.4) p< 0.05)." (PMID 39421446, 2024). "We also discovered a higher rate of CCNE1 amplification among Black patients compared to White patients with uterine serous carcinoma." (PMID 39421446, 2024). "CCNE1 drives the genesis of uterine serous carcinomas mainly by activating cell-cycle progression through CDK2 activation, Rb phosphorylation and E2F-1-mediated transcription." (PMID 27582547, 2017). "Furthermore, fadraciclib combined with a PI3K inhibitor showed synergistic toxicity in serous uterine carcinoma with CCNE1 amplification." (PMID 38184514, 2024). "Additionally, alterations in FBXW7 and CCNE1, both involved in cell cycle regulation, have been found in 20% of uterine serous carcinomas." (PMID 39421446, 2024).
endometriosis (6 papers, 2018 to 2025). The growth of functional endometrial tissue in anatomic sites outside the uterine body. "Luteolin, could inhibit the development of endometriosis by regulating the expression of PI3K/Akt signaling, the MAPK signaling pathway, and CCNE1 protein in human VK2/E6E7 and End1/E6E7 cell lines and in the endometriosis mouse model." (PMID 32210799, 2020).
Ewing sarcoma (6 papers, 2016 to 2026). A small round cell tumor that lacks morphologic, immunohistochemical, and electron microscopic evidence of neuroectodermal differentiation. "In Ewing sarcoma, for instance, KDM5B attenuates FBXW7 transcription, leading to CCNE1 accumulation and enhanced proliferation." (PMID 40370434, 2025).